SEMA3A (semaphorin 3A)
Diseases named in the same sentence as SEMA3A in open-access papers (continued):
Sharing a sentence is not in itself a finding about the gene and the disease.
autoimmune disease (13 papers, 2013 to 2025). A disorder resulting from loss of function or tissue destruction of an organ or multiple organs, arising from humoral or cellular immune responses of the individual to their own tissue constituents. "Several studies have linked pathogenesis of autoimmune diseases to lower Sema3A levels and serum levels were reported to inversely correlate with disease activity of SLE, RA and SSc." (PMID 32210960, 2020). "Studies conducted in our lab strengthened the fact that Sema3A is a key regulatory immune player, especially in autoimmune diseases, e.g., SLE and RA patients." (PMID 41303643, 2025). "Among them, semaphorin 3A is important in downregulating autoimmune diseases, semaphorin 3E as a critical factor for protective immunity against intracellular chlamydia muridarum infection, and semaphorin 4C in protecting against allergic inflammation." (PMID 35734166, 2022). "The members of the semaphorin 3 family that function in pathogenesis of autoimmune diseases are Sema3A, Sema3C, Sema3E, and Sema3F." (PMID 32210960, 2020). "As a growth and apoptosis-related gene, the role of Sema3A had been explored in traumatic brain injury, autoimmune disease and tumors." (PMID 32065781, 2020). "In this review, we discussed the role of immune semaphorins, Sema3A, 3C, 3E, 3F, 4A, 4D, 5A, 6D, and 7A in angiogenesis and autoimmune diseases." (PMID 32210960, 2020). "In terms of its possible use in treating autoimmune diseases, Sema3A is a viable candidate as it has been shown to have immunoregulatory activities on both innate and adaptive immunity." (PMID 32210960, 2020). "Some studies have shown that SEMA3A is down-regulated in some autoimmune diseases such as SLE, RA,SSc and psoriasis." (PMID 29308627, 2018). "SEMA3A is decreased in the immune system of experimental autoimmune encephalomyelitis murine model of multiple sclerosis, which is one of autoimmunity diseases." (PMID 28316886, 2017). "Sema3A is involved in immune responses, and its expression levels are altered in several autoimmune diseases." (PMID 23343469, 2013). "It is believed that Sema3A may play a beneficial role in the pathogenesis of psoriasis and other autoimmune diseases, and the administration of exogenous Sema3A may provide a new perspective for their treatment." (PMID 38139064, 2023). "Considering the role of SEMA3A and its down-regulation in some autoimmune diseases,as well as our bioinformatics predictions, we assumed that miR-145-5p might affect SEMA3A expression." (PMID 29308627, 2018). "Sema3A may, therefore, be of therapeutic value not only as an anti-inflammatory agent in autoimmune diseases and cancer, but potentially in preventing the development of heart failure by limiting adverse cardiac remodeling." (PMID 28540528, 2017). "In the co-culture of Sema3A with Treg cells, there was an increase in the number of Treg cells and an improvement in their function, suggesting that Sema3A may represent a promising new therapeutic strategy for treating autoimmune diseases." (PMID 38139064, 2023). "In autoimmune diseases such as SLE, RA and inflammatory bowel disease (IBD), reduced values of Sema3A were found in the blood in correlation with disease activity." (PMID 38139064, 2023). "Sema3A could therefore be added to the arsenal of treatment options for MS, SLE and other autoimmune disorders." (PMID 32210960, 2020). "Based on our literature review, there was no study onmiR-145-5p effect on SEMA3A in autoimmune diseases tomake a comparison with our results." (PMID 29308627, 2018). "Here again, when purified B cells were co-cultured with recombinant sema3A, we noticed a significant upregulation of CD72 in both the normal controls and SLE patients (though they were lower than in the normal controls), suggesting its beneficial usage in many autoimmune diseases." (PMID 29670620, 2018).
pancreatic cancer (13 papers, 2015 to 2024). "Semaphorin signaling seems to play an important role in the development of pancreatic cancer, with a high frequency of mutations in SEMA3A and SEMA3B." (PMID 32520974, 2020). "A somatic mutation in the plexin-A1 sema3A receptor was linked to enhanced proliferation and invasion in pancreatic cancer cells in response to sema3A." (PMID 30696103, 2019). "The characterisation of the immune microenvironment in murine pancreatic tumours established from cells displaying different Sema3a statuses suggested profound remodelling of the TME by tumour-derived SEMA3A." (PMID 38670629, 2024). "For instance, increased expression of SEMA3A reduces invasion and metastasis induced by the resistance to sunitinib in both cervical and pancreatic cancer." (PMID 32241267, 2020). "We selected the PLXNA1 c.2587G>A variant for further study for a number of reasons: Gene expression studies have recently implied plexin A receptor–SEMA3A signaling in pancreas cancer progression." (PMID 26962861, 2016). "High expression levels of the PLXNA1 receptor and semaphorin 3A (SEMA3A) ligand on the other hand were measured in patients with shorter survival suggest a gain-of-function of these AGs in pancreas cancer." (PMID 26962861, 2016). "In one recent example, in a genomic characterization of pancreatic ductal adenocarcinoma (the major type of pancreatic cancer) high expression of Sema3A and PlxnA1 was found to co-segregate with poor patient survival." (PMID 25624520, 2015). "In addition to NRP‐1, SEMA3a and plexins are overexpressed in pancreatic cancer and are correlated with poor patient outcome." (PMID 30216699, 2018). "However, miR-192 serves as a poor prognosis marker in other cancer types including neuroblastoma targeting Dicer1, gastric cancer targeting RAB11-FIP2 and SMG-1, NSCLC targeting the FGFR3/RB1 pathway, hepatocellular carcinoma targeting SEMA3A, and pancreatic cancer targeting SIP1." (PMID 33614788, 2021). "Indeed, it was recently reported that a mutated sema3A, that unlike natural sema3A binds directly to the plexin-A4 receptor and not to neuropilin-1, is a better inhibitor of angiogenesis as compared to wild type sema3A and strongly inhibits the progression of pancreatic cancer in mouse models." (PMID 30696103, 2019). "This included elements of the Hedgehog signaling pathway (SHH, GAS1), semaphorin signaling (SEMA3A, PLXNA1, PLXNB2, PLXND1, PLXNA2, FARP1, FARP2) and also axon guidance pathways (ROBO1, SLIT1, SLIT3 and SLITRK2), all notable for their involvement in pancreatic cancer progression and metastasis." (PMID 36429078, 2022). "The study of Sema3A and its receptors, such as plexinsA1-A4 (PLXNA1-A4) and neuropilin-1 (NRP1) in PC, demonstrates that SEMA3A had no impact on the growth or survival of pancreatic tumor cells and was upregulated in PC." (PMID 36713527, 2022).
hepatocellular carcinoma (12 papers, 2016 to 2024). A malignant tumor that arises from hepatocytes. "miRNA‐192‐5p was found to promote the proliferation and metastasis of hepatocellular carcinoma cells by interacting with SEMA3A to decrease SEMA3A expression." (PMID 39177014, 2024). "In hepatocellular carcinoma, for instance, miR-192-5p promoted the proliferation and metastasis of the tumor cells by targeting semaphorin 3A (SEMA3A)." (PMID 38839751, 2024). "miR-192-5p promoted hepatocellular carcinoma cell proliferation and metastasis through regulating SEMA3A expression." (PMID 32013999, 2020). "In hepatocellular carcinoma, a significant correlation was reported between the expression of SEMA3A and the number of intra-tumoral macrophages, especially M2 type of TAM27." (PMID 31205625, 2019). "Up-regulation of Sema3A expression promoted tumor growth and tumor progression in a hepatocellular carcinoma (HCC) mouse model by enhancement of the expression of CapG, galectin-3, enolase 2 and Epithelial cell adhesion molecule (EpCAM)." (PMID 30696103, 2019). "Overexpression of SEMA3A promotes tumor progression and predicts poor prognosis of patients with hepatocellular carcinoma after curative resection, consistent with its similar effect on OS of patients with ESCC in the present study." (PMID 29784063, 2018). "For instance, miR-192-5p promotes the proliferation and metastasis of hepatocellular carcinoma cells by targeting SEMA3A." (PMID 30020984, 2018). "Furthermore, one study has shown a positive correlation between Sema3A and the metastatic potential of hepatocellular carcinoma." (PMID 32192122, 2020). "We observed an eightfold increase in SEMA3A expression, which could not be observed in the human hepatoma cell line HepG2." (PMID 39196233, 2024).
diabetes (11 papers, 2013 to 2024). "The genetic ablation and inhibition of SEMA3A signaling ameliorated diabetes-induced kidney dysfunction." (PMID 37835781, 2023). "Increased SEMA3A expression was found in db/db kidneys, as well as streptozotocin-induced-diabetes mouse kidneys." (PMID 37835781, 2023). "Diabetes impairs bone formation and strength in rat femurs by suppressing the expression of Sema3A, β-catenin, and IGF-1." (PMID 35045890, 2022). "In mice, streptozotocin-induced diabetes or oxygen-induced retinopathy upregulates Sema3A expression in the ganglion cell layer." (PMID 35045890, 2022). "Urinary Sema3A also increased as early as two weeks after induction of diabetes and increased over time in conjunction with the development of nephropathy." (PMID 32781674, 2020). "Podocyte Vegf164 overexpression has increased VEGF receptor 2 and Sema3A levels and dramatically worsened diabetic nephropathy in a streptozotocin induced mouse model of diabetes." (PMID 32781674, 2020). "Sema3A pretreated BMSC or adipose mesenchymal stem cells (ASC) have shown therapeutic effects for new bone formation in type 2 diabetes mellitus rats." (PMID 32781674, 2020). "Sema3A pretreated BMSC or adipose mesenchymal stem cell (ASC) sheets show therapeutic effects for new bone formation in type 2 diabetes mellitus rats." (PMID 32781674, 2020). "In the current work, we looked at the role of A2A receptor stimulation and Sema3a levels in the spinal cord in peripheral neuropathy using an animal model with HFD-induced diabetes." (PMID 32566683, 2020). "Genetic ablation of Sema3A, or pharmacological inhibition with a novel Sema3A inhibitory peptide, protected against diabetes-induced albuminuria, kidney fibrosis, inflammation, oxidative stress and renal dysfunction." (PMID 32781674, 2020). "The purpose of this study was to investigate the influence of the complexes of an adipose-derived stem cell sheet (ASC sheet) and Bio-Oss® bone granules on bone healing in type 2 diabetes mellitus (T2DM) rats with the addition of semaphorin 3A (Sema3A)." (PMID 31467560, 2019). "Interestingly circulating semaphorin 3A is also upregulated after induction of diabetes." (PMID 23469280, 2013). "Concomitant upregulation of SEMA3A and NRP2 demonstrated in the present analysis indicates that diabetes induces M2-like macrophages through an autocrine mechanism." (PMID 34222276, 2021). "We examined the expression of A2ARs and Sema3a, as well as Neuropilin 1 and Plexin A, the coreceptors of Sema3a, in the dorsal horn of the lumbar spinal cord of an animal model with HFD-induced diabetes." (PMID 32566683, 2020). "The aim of our study was to highlight the role of sema3a on osteoblast differentiation of MC3T3-e1 in high-glucose condition and explore its therapeutic effect of diabetic osteopathy in vitro and vivo." (PMID 31481931, 2019). "In the meantime, we found that exogenous sema3a did not affect glucose metabolism and body weight in diabetic osteopathy." (PMID 31481931, 2019). "Both, in animal models for MASLD (with or without diabetes) and in primary human LSECs (from both male and female donors) treated with palmitic acid, expression of Sema3a/SEMA3A is substantially enhanced, revealing how this defenestrating (angiocrine) signal is induced by DIO." (PMID 39196233, 2024). "It revealed that sema3a was not a therapeutic method for diabetes." (PMID 31481931, 2019).
Kallmann syndrome (11 papers, 2012 to 2026). Kallmann syndrome (KS) is a developmental genetic disorder characterized by the association of congenital hypogonadotropic hypogonadism (CHH) due to gonadotropin-releasing hormone (GnRH) deficiency, and anosmia or hyposmia (with hypoplasia or aplasia of the olfactory bulbs). "The alteration of the SEMA3A gene is most frequently associated with anosmia, delayed puberty, micropenis, and low serum testosterone in males with KS." (PMID 41532366, 2026). "The study identified a novel SEMA3A exons 6–9 deletion variant in Kallmann syndrome that impairs GnRH neuronal migration and alters cell migration, gonad development, and synaptic pathways." (PMID 41532366, 2026). "Heteroinsufficiency of SEMA3A or its receptor PLXNA1 is implicated in Kallmann syndrome, a genetic disorder with neurological defects in odor detection." (PMID 37941606, 2023). "SEMA3A (Semaphorin 3A) was first linked to the aetiology of Kallmann syndrome by the identification of a heterozygous 213-kb deletion in an individual with from a non-consanguineous family with several affected individuals." (PMID 36517585, 2023). "Moreover, Chd7-deficient Xenopus embryos have reduced semaphorin-3a (sema3a) expression suggesting that disturbed sema3a signaling contributes to the pathogenesis of the CHARGE-related disorder Kallmann syndrome and possibly CHARGE syndrome itself." (PMID 29367567, 2016). "The proband exhibited anosmia, suggesting a possible link between SEMA3A gene defects and olfactory dysfunction." (PMID 41532366, 2026). "In Kallmann syndrome, anosmia/hyposmia is part of the clinical picture, and ANOS1, CHD7, FGFR1, PROK2, PROKR2, and SEMA3A variants were reported to be involved in isolated congenital anosmia." (PMID 32222824, 2021). "We also ruled out oligogenism by sequencing the main genes associated with nCHH and Kallmann Syndrome, although WDR11, CHD7 and SEMA3A, other genes known to be associated with CHH, have not been analyzed." (PMID 23936060, 2013).
myocardial infarction (11 papers, 2013 to 2025). Gross necrosis of the myocardium, as a result of interruption of the blood supply to the area, as in coronary thrombosis. "SEMA3A was responsible for progression of myocardial infarction, but this gene may be associated with pathogenesis of CAD." (PMID 31881747, 2019). "It was also reported that SEMA3A expression in circulating monocytes was increased in patients 30 days after myocardial infarction." (PMID 37835781, 2023). "On the contrary, after myocardial infarction there is increased expression of SEMA3A on circulating monocytes, and stimulation of classically activated monocytes with recombinant SEMA3A promotes their transition towards a resolution phenotype." (PMID 34012455, 2021). "In the murine model of myocardial infarction, 3 days after myocardial infarction Sema3A gene expression increased significantly in the areas bordering the infarcted tissue (p < 0.05), returning back to baseline levels after 14 days (p < 0.005)." (PMID 28540528, 2017). "In patients, 30 days post myocardial infarction, circulating monocytes have increased expression of Semaphorin3A (Sema3A) as compared to directly after admission." (PMID 28540528, 2017). "Collectively our data demonstrate that Sema3A reduces cardiac inflammation and improves cardiac function after myocardial infarction by promoting the resolution of inflammation." (PMID 28540528, 2017). "Whilst infarct sizes were similar 14 days after myocardial infarction in both genotypes, Sema3A HZ mice had thinner infarcts and reduced cardiac function as compared to their WT littermates." (PMID 28540528, 2017). "Although further studies are still required to conclude, SEMA3A signaling might be involved in the CRS after myocardial infarction." (PMID 37835781, 2023). "Sema3A WT and HZ mice were subjected to the mouse model of myocardial infarction." (PMID 28540528, 2017). "Furthermore, SEMA3A exerts protective effects in myocardial infarction (MI)." (PMID 37291626, 2023). "It is the first study to demonstrate a role for Sema3A in promoting the resolution of inflammation after AMI which may be in line with the increased expression of Sema3A in monocytes of human subjects following myocardial infarction." (PMID 28540528, 2017). "In the context of myocardial infarction, GAS5 was demonstrated to ameliorate cardiomyocyte apoptosis and reduce infarct size in vivo by negatively regulating semaphorin 3a (sema3a)." (PMID 39941145, 2025). "With regard to injury in the adult heart, Sema3A was shown to be increased in response to chronic ISO infusion in rats and to ameliorate electrical remodeling after myocardial infarction in rats." (PMID 24901703, 2014). "We investigated whether overexpression of Sema3a in the myocardial infarction (MI) border zone could attenuate sympathetic hyper-innervation and decrease the vulnerability to malignant ventricular tachyarrhythmia (VT) in rats." (PMID 23711091, 2013). "Furthermore, decreased Sema3A levels did not result in significant changes in the amount of leukocyte subsets present in the circulation 3 days after myocardial infarction." (PMID 28540528, 2017).
Stroke (11 papers, 2010 to 2025). Sudden impairment of blood flow to a part of the brain due to occlusion or rupture of an artery to the brain. "Complicating potential functions in post-stroke axonal pathfinding, Semaphorin 3A in the adult brain is also clearly associated with neuronal apoptosis." (PMID 20505770, 2010). "Sema3A is closely associated with ischemic stroke and affects stroke recovery." (PMID 35350431, 2022). "It has been found that semaphorin 3A is closely related to ischemic stroke and is effective in the recovery of stroke." (PMID 41303895, 2025). "This increase in brain inflammation exacerbates stroke volume and worsens functional outcomes in Mrgprb2−/− mice, demonstrating that Sema3a inhibition is sufficient to allow Mrgprb2−/− mice to phenocopy WT mice." (PMID 40712576, 2025). "This study aimed to assess rTMS’s effect on post-stroke endogenous neuroplasticity by dosing plasma miRs 17~92, Netrin-1, Sema3A, and BDNF." (PMID 38540283, 2024). "Stroke induction increases Sema3A in the cortex for up to 2 weeks and is detrimental to the damaged brain." (PMID 33978913, 2022). "Semaphorin 3A and 4A levels were significantly associated with inflammatory and prothrombotic blood parameters, while semaphorin 7A levels correlated with the NIHSS stroke score, suggesting potential prognostic value." (PMID 41303895, 2025). "Sema3A and Ntn-1 participate in post-stroke brain remodeling in rats." (PMID 38540283, 2024). "We also measured levels of Ntn-1 and Sema3A as peripheral markers for post-stroke axogenesis." (PMID 38540283, 2024). "To determine whether this decrease in Sema3a is a driving force for immune cell migration from the dura to the brain, we hypothesized that inhibition of Sema3a should increase neutrophil migration into the brain and exacerbate brain inflammation after stroke." (PMID 40712576, 2025). "Specific changes related to tissue remodeling and cell migration observed in the core and the PI areas included SEMA3A and SEMA4F (downregulated 24 h after stroke in the PI area)." (PMID 23284893, 2012). "Further, Sema3a inhibition does not worsen WT brain inflammation after stroke, suggesting that Sema3a is already inhibited in WT mice after tMCAO." (PMID 40712576, 2025). "Indeed, we see by ELISA of leptomeningeal lysates that semaphorin 3a (Sema3a), but not semaphorin 3d, is specifically decreased in WT, but not Mrgprb2−/− mice after stroke." (PMID 40712576, 2025). "Our results show that an increase in Sema3A levels post-ONC leads to a significant up-regulation of M1-like microglia and a concomitant decrease in M2-like microglia, consistent with the dynamic changes of M1/M2 phenotype after traumatic brain injury and stroke." (PMID 34039431, 2021).